ACE (angiotensin I converting enzyme)
Diseases named in the same sentence as ACE in open-access papers (continued):
Sharing a sentence is not in itself a finding about the gene and the disease.
chronic pancreatitis (6 papers, 2006 to 2025). A chronic inflammatory process causing damage and fibrosis of the pancreatic parenchyma. "Animal studies also show that angiotensin-converting enzyme (ACE) inhibitors alleviate chronic pancreatitis and are suggested as a potential treatment for CP." (PMID 35431983, 2022). "In male WBN/Kob rats, ACE-Is (lisinopril) reduced the fibrosis characterizing chronic pancreatitis." (PMID 37509613, 2023). "In addition, ACE inhibitors have recently been demonstrated to attenuate pancreatic inflammation and fibrosis in spontaneously occurring chronic pancreatitis in male Wistar Bonn/Kobori rats." (PMID 17163998, 2006).
cyst (6 papers, 2013 to 2024). A sac-like closed membranous structure that may be empty or contain fluid or amorphous material. "No other pathogenic variants were found in other ADPKD-associated genes (PKDH1, GANAB, ACE, etc,) or related to cyst progression." (PMID 35327948, 2022). "Several studies in animal models of PKD have shown that ACE inhibitors decreased cyst formation and improved renal function." (PMID 28197498, 2016). "Polycystic kidney disease has been reported to be resistant to ACE inhibitor treatment and to progress relentlessly even after inhibition of cyst development." (PMID 24349134, 2013). "Presence of RAAS components (AGT, ACE, ANG II and angiotensin II type I receptor) within cysts and tubules and activation of RAAS during cyst expansion in ADPKD has also been demonstrated." (PMID 28197498, 2016). "Histological results suggest possible mechanisms involving diffuse alveolar damage, check-valve formation in the bronchus, direct virus-induced airway injury via the angiotensin-converting enzyme (ACE) II receptor, and traction of fibrous tissue around the cyst." (PMID 39030558, 2024).
diabetic neuropathy (6 papers, 2015 to 2025). A chronic, pathological complication associated with diabetes mellitus, where nerve damages are incurred due to diabetic microvascular injury involving small blood vessels that supply these nerves, resulting in peripheral and/or autonomic nerve dysfunction. "Furthermore, exploring additional polymorphisms within the ACE gene and associated pathways could yield a more nuanced understanding of the genetic underpinnings of diabetic neuropathy." (PMID 41002725, 2025). "Several genes have been linked to diabetic neuropathy, but only two, ACE (angiotensin-converting enzyme) and MTHFR (methylenetetrahydrofolate reductase) polymorphisms, have been studied in large cohorts." (PMID 41169500, 2025). "ACE inhibitors are well-known antihypertensives, and aldose reductase inhibitors have been tested as drugs for diminishing the effects of diabetic neuropathy." (PMID 34577613, 2021). "This review suggests that polymorphism within ACE, AKR1B1, APOE, MTHFR, NOS3, and VEGF may act as common genetic risk factors for the diabetic neuropathies in T2DM." (PMID 26074879, 2015).
glioma (6 papers, 2006 to 2024). A benign or malignant brain and spinal cord tumor that arises from glial cells (astrocytes, oligodendrocytes, ependymal cells). "ACE DD genotype were highly presented in glioma cases (63.9%) than controls (33.8%) and conferred 3.64-fold risk for predisposition in glioma cases (vs ID genotype, p<0.001)." (PMID 31312309, 2019). "In glioma cases, allelic frequencies and genotypes distribution of the ACE I/D polymorphism were different from controls cases." (PMID 31312309, 2019). "The present study was interested in potential association between ACE I/D polymorphism and glioma in Algerian population." (PMID 31312309, 2019). "The expression of ACE gene was detected by polymerase chain reaction restriction fragment length polymorphism (PCR-RFLP) analysis in 36 Algerian patients with glioma and 195 healthy controls." (PMID 31312309, 2019). "The ACE gene I/D polymorphism has been linked to many cancers with a very few researches on glioma." (PMID 31312309, 2019). "Therefore, the aim of the present study was to evaluate the potential association between ACE I/D polymorphism and glioma in Algerian population and consequently on its potential role for developing therapeutic drug targets for this cancer." (PMID 31312309, 2019). "Therefore, the present study was concerned with the investigation of an eventual association between glioma and I/D polymorphism of the ACE gene." (PMID 31312309, 2019). "Recently, the ACE I/D polymorphism was linked to the pathogenesis and progression of several cancers such as lung, digestive, breast, laryngeal, prostate cancers and last in glioma." (PMID 31312309, 2019). "Likewise, the DD genotype predisposed risk of glioma by more than 3-fold i.e. 63.9 and 33.8% in glioma cases and controls, respectively (p<0.001), indicating the potential of ACE I/D polymorphism as a predictive marker in glioma." (PMID 31312309, 2019). "The obtained data suggest that the ACE I/D polymorphism could be a risk factor for glioma." (PMID 31312309, 2019). "Moreover, the impact of studies on ACE I/D polymorphism in glioma was also therapeutic." (PMID 31312309, 2019). "Nevertheless, a study with a large sample and a follow-up study to analyze glioma overall survival by ACE I/D genotype are necessary." (PMID 31312309, 2019). "In another recent study in Indian population: ACE DD genotypes were highly presented in glioma cases compared to controls with 26.8% and 10.6%, respectively (p<0.0001) and conferred 5-fold risk for predisposition in glioma cases." (PMID 31312309, 2019). "Out of these NRGs, 19 NRGs (EGLN3, HILPDA, HMBS, HYOU1, BNIP3, etc.)were found to be enriched in glioma tissues while 13 genes (SLC4A1, IL6, EPAS1, ACE, HMOX1, etc.)were decreased compared to normal tissues." (PMID 37934582, 2023). "For instance, ACE inhibitors and angiotensin II inhibitors are both classified in ATC group C09, but might differ in their ability to induce or promote glioma." (PMID 16495922, 2006).
Headache (6 papers, 2008 to 2024). Cephalgia, or pain sensed in various parts of the head, not confined to the area of distribution of any nerve. "Our study also indicates that ACE genotyping will not be a valuable tool for predicting clinical response of drugs influencing the angiotensin system in headache treatment." (PMID 18366776, 2008).
hemorrhagic stroke (6 papers, 2008 to 2024). A stroke caused by a bleed on the brain. "The population-attributable risks (PARs) for gene variants with the most reliable associations for haemorrhagic stroke in this study were 9.24% for the ACE/ID polymorphism and 7.78% for the SERPINE1 4G/5G." (PMID 19008959, 2008). "Although some studies have described the DD genotype as a potent thrombophilic factor, several studies have reported that D allele carriers of ACE have increased risk of hemorrhagic stroke and blood loss after hip surgery, which is also consistent with our results." (PMID 34451921, 2021). "Statistically significant associations with haemorrhagic stroke were identified for those homozygous for the ACE/I allele (OR, 1.48; 95% CI, 1.20–1.83; p = 0.0003) and for the 5G allele in the SERPINE1 4G/5G polymorphism (OR, 1.42; 95% CI, 1.03–1.96; p = 0.03)." (PMID 19008959, 2008). "Nevertheless, given the high incidence of haemorrhagic stroke (100,000 per year in the United States), if these estimates hold true they suggest that common variants in the ACE and SERPINE1 genes alone may contribute between 8,000–10,000 haemorrhagic strokes in the United States each year." (PMID 19008959, 2008). "In addition to examining the association of the ACE/DD genotype with haemorrhagic stroke, several studies have suggested that the ACE/II genotype may be associated with haemorrhagic stroke." (PMID 19008959, 2008). "Additionally, polymorphisms in genes such as ACE (angiotensin-converting enzyme), COL4A2 (type IV collagen alpha 2 chain), and MTHFR (methylenetetrahydrofolate reductase) have also been implicated in increasing the risk of hemorrhagic stroke." (PMID 39497863, 2024).
leiomyoma (6 papers, 2019 to 2024). A well-circumscribed benign smooth muscle neoplasm characterized by the presence of spindle cells with cigar-shaped nuclei, interlacing fascicles, and a whorled pattern. "A total of eight leiomyoma-related DEGs (EGR1, CEBPB, IL6, PECAM1, VWF, TNFRSF1A, CD34 and ACE) were found upregulated in MF versus M only." (PMID 33807176, 2021). "Although the mechanism by which ACE polymorphism may affect this complication has not been elucidated yet, the importance of the attention to RAS system polymorphisms in leiomyoma is considerable." (PMID 31554351, 2019).
lupus nephritis (6 papers, 2011 to 2025). Glomerulonephritis in the context of systemic lupus erythematosus. "Moreover, anti-ACE 2 inversely correlated with total protein and albumin after six months of observation in the lupus nephritis group." (PMID 40364208, 2025). "For example, genetic variants in genes expressed in the kidney (including TNFRSF1B, KLK1, KLK3, ACE, AGT, and APOL1) may result in increased susceptibility to kidney injury and, as a result, in progression to lupus nephritis." (PMID 39124752, 2024). "Because polymorphisms in ACE are associated with the activity of SLE and lupus nephritis and based on well-documented renal-protective effects of Renin Angiotensin System (RAS)-modifying therapies, ACE-I are now widely used in patients with SLE with significant efficacy." (PMID 32793221, 2020). "Polymorphisms in ACE are associated with the activity of SLE and lupus nephritis." (PMID 32793221, 2020). "Fifth, due to lack of sufficient data, we were not able to study lupus nephritis individually in relationship with ACE allele in this meta-analysis." (PMID 30618805, 2018). "Lupus nephritis patients not using ACE inhibitor have shown association with increased carotid atherosclerosis." (PMID 30618805, 2018). "However, the interruption of the renin angiotensin with ACE inhibitors or angiotensin receptor blockers (ARBs) is recommended as first line adjuvant therapy for the patients with lupus nephritis for proteinuria." (PMID 30618805, 2018). "In this study, antroquinonol, the major active component of ACE, inhibited the production of TNF-α and IL-1β in LPS-induced RAW 264.7 cells, suggesting that this anti-inflammatory activity may contribute to the function of ACE in attenuation of the progression of lupus nephritis." (PMID 18955361, 2011).
Lymphadenopathy (6 papers, 2021 to 2025). Enlargement (swelling) of a lymph node. "One patient simultaneously developed new intrathoracic lymphadenopathies and elevated serum ACE levels, with biopsy confirming a sarcoid-like reaction." (PMID 40689241, 2025). "In contrast, our patient's normal ACE levels and absence of lymphadenopathy prolonged diagnostic uncertainty." (PMID 41179272, 2025). "A chest CT scan showed lymphadenopathy in his bilateral hilar regions and a granular shadow in his right lung despite no elevation of serum angiotensin-converting enzyme (ACE) or lysozyme." (PMID 38005993, 2023). "As opposed to this clinical phenotype, our case had lymphadenopathy with tenderness and did not have hilar lymphadenopathy, proteinuria, elevated ACE, and other findings such as hepatomegaly, nephrocalcinosis, or nephrolithiasis on CT scan and on Gallium scintigraphy." (PMID 34556154, 2021).
malignant hypertension (6 papers, 2011 to 2025). Severe hypertension that is characterized by rapid onset of extremely high blood pressure and hypertension-mediated organ damage. "It shows that polymorphism in the angiotensin-converting enzyme (ACE) gene is a significant risk factor for the initiation of malignant hypertension." (PMID 36017304, 2022). "The use of beta-blockers, of ACE inhibitors, of dihydropiridinic calcium channel blockers, of clonidine and of diuretics was greater in the group with hypertensive emergencies, possibly reflecting the higher prevalence of comorbidities." (PMID 34420015, 2021). "ACE inhibitors remain the cornerstone of SRC treatment, as they effectively control malignant hypertension and have been shown to improve survival outcomes." (PMID 40725689, 2025).
neutropenia (6 papers, 2020 to 2025). A decrease in the number of neutrophils found in the blood. "Furthermore, the beneficial effects of ACE inhibitors in HF might be partly due to effects on neutrophils, including antiinflammation and neutropenia." (PMID 34793333, 2022).
oligohydramnios (6 papers, 2016 to 2024). A lower than normal quantity of amniotic fluid in the amniotic sac as compared to normal values. "ACE inhibitors also cause fetal renal failure resulting in oligohydramnios." (PMID 37460679, 2023).
pneumonitis (6 papers, 2013 to 2024). An inflammatory process affecting the lung parenchyma. "ACE-inhibitors were able to mitigate radiation-induced pneumonitis through inhibition of ACE expression and decrease in ROS formation." (PMID 39767557, 2024). "We then evaluated the contribution of the irradiated bone marrow (BM) compartment on lung immune cell infiltration and ACE imbalance during pneumonitis." (PMID 37275232, 2023). "Marked improvement in vascular function and survival during pneumonitis have been observed in rats treated with the angiotensin converting enzyme (ACE) inhibitor lisinopril." (PMID 36548580, 2022). "In fact the ACE inhibitor enalapril can be started 5 weeks after radiation to mitigate pneumonitis and fibrosis." (PMID 28303893, 2017). "Additionally, we demonstrate using a bone marrow transplantation model that concurrent injury to the bone marrow exacerbates recruitment of ACE-expressing myeloid cells to the lung during pneumonitis." (PMID 37275232, 2023). "Transplantation of bone marrow from irradiated donors increased both ACE-expressing myeloid cell infiltration and immune ACE activity in the lung during pneumonitis compared to non-irradiated donors." (PMID 37275232, 2023).
polycystic kidney disease (6 papers, 2006 to 2025). A usually autosomal dominant and less frequently autosomal recessive genetic disorder characterized by the presence of numerous cysts in the kidneys leading to end-stage renal failure. "For examples studies on autosomal dominant polycystic kidney patients have reported adverse effects of the D allele of the ACE gene in some cases, whereas number of other studies did not confirmed such association." (PMID 17042963, 2006). "AGT and ACE variants were associated with renal tubular dysgenesis, while PKD1 and PKHD1 mutations indicated both dominant and recessive polycystic kidney disease." (PMID 41288877, 2025). "Meanwhile, ACE expression levels were decreased in polycystic kidney tissue compared to the stain intensity in normal kidney tissue." (PMID 26092580, 2015).
primary aldosteronism (6 papers, 2012 to 2025). An endocrine disorder characterized by excessive production of aldosterone by the adrenal glands. "One subtype includes patients with elevated plasma aldosterone levels, such as those associated with primary aldosteronism, and those who experience “aldosterone escape” or “aldosterone breakthrough” during therapy with ACE inhibitors or ARBs." (PMID 31239535, 2019). "Medications that interfere with the renin-angiotensin-aldosterone system - particularly ACE inhibitors and mineralocorticoid receptor antagonists - can mask primary aldosteronism by altering ARR interpretation." (PMID 41356982, 2025). "Moreover, in primary aldosteronism, after challenge with ACE inhibitors, the plasma aldosterone concentration fell more in anti-AT1-AR positive individuals than in negative individuals, suggesting that this autoantibody plats an agonistic role." (PMID 24175973, 2013).
Proteinuria (6 papers, 2011 to 2021). Increased levels of protein in the urine. "Our experience demonstrate that nephrotic proteinuria associated with a mild form of SIOD may respond to combined therapy with ACE- inhibitors and sartans, supporting the concept that several missense mutations in SMARCAL1 gene retain some residual function." (PMID 24589093, 2014). "Proteinuria (> 300 mg/day) was present in 62.8% of the subjects with a mean of 1.2 ± 1.8 g/24 hrs) despite of the widespread use of ACE-inhibitors and ARB drugs." (PMID 21970625, 2011). "At the time of study start 30 (91%) patients were treated with an ACE-inhibitor or angiotensin ll-receptor-blocker, 20 (61%) patients received diuretics, 15 (45%) patients received statins and five (15%) patients received anticoagulants, although they had non-nephrotic proteinuria." (PMID 25313791, 2014).
psychosis (6 papers, 2012 to 2026). "This review synthesizes evidence on ACE-III and M-ACE in psychosis-related neurodegeneration, highlights their role in differentiating from primary psychiatric psychoses, and identifies knowledge gaps, particularly in atypical AD variants, mixed dementia, and autosomal dominant AD." (PMID 42194406, 2026). "The frequency of the homozygous DD genotype of the ACE gene was significantly increased in patients with PD, and is also higher in PD patients with L-dopa-induced psychosis versus without psychosis." (PMID 22619734, 2012).
respiratory infections (6 papers, 2020 to 2025). "Other associated conditions are recent or active respiratory infection, smoking, and use of angiotensin-converting enzyme (ACE) inhibitors." (PMID 37160771, 2023).
scleroderma (6 papers, 2005 to 2025). Scleroderma is a rare autoimmune connective tissue disorder characterized by abnormal hardening of the skin and, sometimes, other organs. "She did not respond to ACE inhibitors because she did not have classical scleroderma renal crisis." (PMID 18474117, 2008). "All other rheumatologic and infectious workups were negative, including HIV, ACE, ANA, ANCA, CRP, anti-scleroderma antibody and HCV." (PMID 40038144, 2025).
secondary hypertension (6 papers, 2016 to 2025). High blood pressure caused by an underlying medical condition. "In cases of persistent or secondary hypertension, pharmacological therapy may be indicated, with agents such as ACE inhibitors, angiotensin receptor blockers, calcium channel blockers, or beta-blockers selected based on the underlying condition and patient tolerance." (PMID 40142719, 2025).
systemic sclerosis (6 papers, 2005 to 2026). A chronic disorder, possibly autoimmune, marked by excessive production of collagen which results in hardening and thickening of body tissues. "It was also noted that a meta-analysis evaluating the prognosis of SRC in systemic sclerosis (SSc) reported significantly poorer outcomes in patients with prior exposure to ACE inhibitors." (PMID 40725689, 2025).
valvular heart disease (6 papers, 2013 to 2023). "Sex, BMI, smoking, serum lipids, HbA1c, CKD, history of previous CHD and mild valvular heart disease, and use of ACE-inhibitors, angiotensin receptor antagonists, beta blockers, lipid-lowering, anti-platelet and hypoglycemic drugs did not significantly differ between the groups." (PMID 23451184, 2013).
ventricular dilatation (6 papers, 2011 to 2025). "In the present study, both early and delayed ACE inhibitor therapies improved ejection fraction and attenuated ventricle dilatation at 8 weeks, suggesting an independent benefit of early anti-inflammatory therapy for late function." (PMID 32125488, 2020). "CCBs are the alternatives to beta-blockers in the treatment of HTN in patients with CHD but are not recommended for secondary cardiac prevention because of their inability to prevent ventricular dilatation, especially when compared to ACE inhibitors or ARBs." (PMID 23476746, 2013). "Suppression of angiotensin activity either by inhibition of angiotensin-converting enzyme (ACE) or by blockade of angiotensin II receptor attenuates ventricular dilatation and improves clinical outcomes." (PMID 22108275, 2011).